TLR4 (toll like receptor 4)
Diseases named in the same sentence as TLR4 in open-access papers (continued):
Sharing a sentence is not in itself a finding about the gene and the disease.
Sepsis (continued). "eCIRP is well known be increased in sepsis conditions and to promote inflammation via binding to the TLR4/MD2 complex and displays a strong interaction to this complex." (PMID 36782115, 2023). "Taken together, our study presents the potential role of rhamnetin in protecting against oxidative damage induced by CRAB infection through a TLR4 and ROS-mediated pyroptotic pathway, showing an alternative mechanism for sepsis prevention." (PMID 37958587, 2023). "The myocardial dysfunction in sepsis is influenced by Toll-like receptor 4 (TLR4)-mediated signaling pathways, which induce inflammation and the generation of reactive oxygen species (ROS)." (PMID 37900069, 2023). "For example, in sepsis, immunosuppressive monocytes have reduced responsiveness to LPS (TLR4 stimulation), consistent with dysregulated response to future bacterial infection in these patients." (PMID 37968278, 2023). "Our studies do in fact show that PS-OMe miR130 is highly stable, and functions by blocking the interaction between eCIRP and TLR4, which in turn reduced injury and inflammation, and improved survival in sepsis." (PMID 36782115, 2023). "Inhibitors of the TLR-4 pathway have been investigated in varius diseases and showed positive effects aginst sepsis, cerebral ischemia, and inflammatory bowel disease." (PMID 37292209, 2023). "Studies reported that peptides as a competitive inhibitor for the TLR4 adaptors ameliorated LPS-induced sepsis, collagen-induced arthritis and systemic lupus erythematosus in mouse models." (PMID 37215126, 2023). "During severe sepsis, the TLR4 signaling pathway mediates harmful and excessive inflammatory responses." (PMID 38455195, 2023). "LPS triggers a Toll-like receptor 4 (TLR4) signaling cascade and causes a systemic inflammatory response, leading to organ dysfunction or sepsis due to uncontrolled inflammatory signaling during infection." (PMID 37958587, 2023). "During early sepsis, macrophages’ toll-like receptor 4 (TLR4) recognizes LPS, activating the nuclear factor-κB (NF-κB) and mitogen-activated protein kinase (MAPK) pathways to release proinflammatory cytokines and clear pathogenic microorganisms." (PMID 38114466, 2023). "In a TLR4-induced sepsis animal model, treatment with S. thermophiles alleviates intestinal injury and decreases the serum levels of inflammatory cytokines (IL-6 and TNF-α)." (PMID 36838243, 2023). "According to a previous study, the intestinal dysbiosis profile of a TLR4-induced sepsis animal model differs from that of a TLR3-induced intestinal injury model." (PMID 36838243, 2023). "LPS are commonly used to model sepsis and inflammation in mammals due to their potent pro-inflammatory properties and well-studied TLR4-dependent mechanisms of activation." (PMID 36985596, 2023). "As a classic pathophysiology of sepsis development, the LPS-induced activation of the TLR4/NF-κB signaling pathway has been well defined." (PMID 36675101, 2023). "In sepsis, Shikonin improved sepsis-induced lung injury by modulating the miRNA-140-5p/toll-like receptor-4 (TLR4) pathway." (PMID 38138440, 2023). "In summary, J147 treatment ameliorated neuroinflammation and the depressive-like behaviors of mice suffering from sepsis by inhibiting the TLR4/NF-κB signaling pathway." (PMID 37676534, 2023). "CIRP also triggered endoplasmic reticulum (ER) stress via TLR4 activation in preclinical models of sepsis and promoted inflammation, apoptosis, and histological injury." (PMID 36865547, 2023). "Once sepsis-induced cellular damage occurs, eCIRP, other DAMPs, and endotoxin can activate TLR4 to further exacerbate inflammation." (PMID 37463445, 2023). "Given the evidence for a detrimental effect of the complete suppression of cytokine release in sepsis, compounds that are able to inhibit LPS-induced signaling while maintaining a modest activation of TLR4-mediated responses represent a valuable alternative." (PMID 37630200, 2023).
Sepsis (continued). "TNF-α is widely recognized as a critical mediator in sepsis, and TLR4 plays a central role in initiating signaling pathways that lead to TNF-α production." (PMID 38001481, 2023). "As the liver is one of the key target organs during sepsis, the proteins of TLR4, myD88, and NF‐κB in the livers were assayed to clarify the role of this pathway in the LPS‐induced sepsis." (PMID 38455195, 2023). "In particular, there is strong evidence that the TLR4/NFκB signaling contributes to the pathogenesis of sepsis by increasing the production of inflammatory mediators." (PMID 37255592, 2023). "LPS is a single pathogen-associated molecular pattern (PAMP) which specifically triggers toll-like receptor 4, while sepsis is driven by a wide range of PAMPs." (PMID 37449973, 2023). "Recently, it has been discovered that the TLR-4/NF-κB-mediated signaling pathway is involved in sepsis-induced cardiomyocyte apoptosis." (PMID 38161332, 2023). "The findings suggest that Sulforaphane can decrease heart damage in male mice during CLP-induced polymicrobial sepsis by suppressing TLR-4/NF-kB downstream signal transduction pathways." (PMID 37900081, 2023). "Another animal study suggests that sepsis-induced TLR4 activation upregulates neutrophil infiltration and the expression of proinflammatory cytokines in tubular epithelial cells, resulting in the development of acute kidney injury." (PMID 36674930, 2023). "This study found that PB2 has a significant protective effect against sepsis by inhibiting lung injuries, reducing cytokine storm, and regulating the TLR4/NF-κB and PI3K/Akt signaling pathways via its anti-inflammatory properties by inhibiting Hippo and Rho." (PMID 37175637, 2023). "Actually, the inhibition of the TLR4/NF‐κB signaling pathway attenuates sepsis and its related complications." (PMID 38455195, 2023). "Since S100A8/A9 represents an endogenous ligand of TLR4, it has been manifested to mediate inflammatory cascades during sepsis." (PMID 37337301, 2023). "Additional studies have further demonstrated the importance of TLR4 signaling in sepsis, and that TLR4 is a well-established target for therapeutics." (PMID 36782115, 2023). "It is well-established that the calgranulin S100A8/A9 complex is one of the biomarkers in sepsis and exerts its inflammatory role through TLR4 activation." (PMID 37623960, 2023). "ATP2B1.AS1 is strongly associated with cell inflammation and can regulate the miR-23a-3p/TLR4 axis, exacerbating sepsis-induced cell apoptosis and inflammation." (PMID 37629096, 2023). "By considering the sepsis was caused by LPS, LPS receptor TLR4 signaling was detected via Tlr4 signaling inhibitor TAK242 and Tlr4 knock-out macrophages." (PMID 36707853, 2023). "The up-regulation of TLR4, TLR2, CD62P, and CD32 has been described in sepsis and is associated with an increased ability to bind E. coli bacteria." (PMID 36769137, 2023). "It has long been believed that the robust TLR4 plays a critical role in the pathogenesis of septic shock and sepsis, which mainly regulate the infiltration of inflammatory cells and the production of pro-inflammatory cytokines." (PMID 37049646, 2023). "Our research shows that sepsis can induce a systemic inflammatory response in mice by activating the TLR4/MyD88/NF-κB signalling pathway, thus increasing the mortality of mice." (PMID 38102579, 2023). "In murine sepsis, increased ileal expression of TLR4 promoted the depletion of Paneth cells, and reduced lysozyme and defensin alpha 5 (DEF-5) expression exacerbated intestinal damage, and increased mortality rate." (PMID 38001795, 2023). "Given TRAF6’s essential role in macroautophagy/autophagy activation triggered by TLR4 signaling, and the established connection between autophagy and sepsis-induced cardiomyopathy, we proceeded to treat LPS-induced BMDMs with si-TRAF6." (PMID 37919806, 2023).
Sepsis (continued). "These miRNAs were reported earlier in sepsis patients and in many studies aiming to understand the regulation of signaling molecules in the TLR-4 pathway upon LPS exposure." (PMID 36766397, 2023). "In conclusion, the knockdown of PICK1 appeared to modulate inflammatory factors by activating the TLR4/NF-κB signaling pathway, thereby exacerbating hepatic damage induced by sepsis." (PMID 37488153, 2023). "Currently, TLR4 antagonists are being investigated for their potential in managing inflammatory-based diseases such as sepsis and arthritis." (PMID 35867263, 2023). "During sepsis, TLRs are activated, with TLR4 being involved in endotoxemia by recognizing lipopolysaccharide (LPS) proteins." (PMID 37841241, 2023). "Recently, researchers provided evidence for the contribution of the TLR4-TRAM-TRIF signaling pathway to the late-phase sepsis pathology, more specifically to kidney injury." (PMID 37788908, 2023). "To this end, we developed a BN model for the TLR4-mediated host inflammatory response that plays an important role in the systemic inflammatory response in the early phase of sepsis." (PMID 36261775, 2022). "In contrast to the protective role of LIGHT in cisplatin-induced AKI by increasing mitochondrial apoptosis, we found that LIGHT promotes sepsis-induced kidney injury through the TLR4-MyD88-NF-κB signaling pathway." (PMID 36163116, 2022). "“Addressing inconsistencies in caveolae-sepsis-regulated signaling pathways, including LPS, eNOS, and TLR4." (PMID 36559147, 2022). "As a key molecule to transduce signals from TLR4 to downstream pathways, MyD88 also has crucial roles in sepsis-induced organ injuries." (PMID 35410456, 2022). "TLR4-mediated inflammation by histones has been previously involved in experimental model of sepsis, acute renal injury or glomerulonephritis." (PMID 35562918, 2022). "sesamin improves the 7-day survival rate of septic mice, suppresses the inflammatory response in sepsis through the HMGB-1/TLR4/IL-33 signaling pathway." (PMID 35720285, 2022). "Cav–1 phosphorylation was required for interaction with TLR4 and activation of TLR4–MyD88 signaling and sepsis–induced lung inflammation." (PMID 35911737, 2022). "On one hand, TLR4 inhibition was once considered to be an innovative therapeutic approach targeting pathogen infection, such as sepsis." (PMID 35370674, 2022). "TLR4, a member of pattern recognition receptors that recognize microbial PAMPs, is involved in the regulation of autophagy during sepsis." (PMID 36188562, 2022). "In vitro and in vivo studies found that they play an anti-sepsis role through regulating TLR4-NF-κB by binding to lipid A, which is the active center of LPS (Chen GR." (PMID 36160407, 2022). "As for mechanical ventilation, previous studies have shown that activation of TLR4 in sepsis can induce increased expression of integrin β5, which can cause higher susceptibility to mechanical ventilation-related acute lung injury." (PMID 35573024, 2022). "LSD1 functions downstream of LPS/TLR4 and controls acute inflammatory response during sepsis in myeloid cells." (PMID 35115604, 2022). "On one hand, the expression level of these protein molecules is related to the TLR4-activated inflammatory response, which can be used to evaluate the severity of the infection and predict the occurrence of sepsis." (PMID 36402943, 2022). "Lipopolysaccharides (LPS) are a major component of the cell wall of Gram-negative bacteria and exhibit strong immunostimulatory activity by targeting the TLR4 signaling axis and triggering sepsis inside the body." (PMID 35281916, 2022). "GM-CSF not only improves total leukocyte counts (TLCs) but also reversed the monocytic deactivation by increasing HLADR and TLR4 expression in sepsis patients." (PMID 35720398, 2022). "During sepsis, endotoxin was bonded to TLR4 on S1 proximal tubule cells, which henceforward resulted in oxidative stress in cells of the S2 segment." (PMID 36010680, 2022).
Sepsis (continued). "Of further note, although Toll-like receptor 4 is essential to preserve cardiac function and long-term survival in low-grade polymicrobial sepsis, Toll-like receptor signalling is similar in male and female mice after injury." (PMID 35723764, 2022). "miR-146a also reduces inflammation and inhibits complications of sepsis-induced cardiomyopathy by inhibiting the TLR4/NF-κB signaling pathway." (PMID 39281713, 2022). "Studies have shown that the activation of TLR4 signaling in severe sepsis can enhance the inflammatory response by promoting the release of pro-inflammatory cytokines, causing heart damage, and inhibiting heart function." (PMID 35891967, 2022). "This makes large-scale stratification of sepsis patients for their TLR-4 activation status possible." (PMID 36230982, 2022). "This receptor can recognize LPS and is responsible for initiating the inflammatory cascade, suggesting the potential value of targeting TLR4 in the treatment of sepsis." (PMID 35722155, 2022). "Toll-like receptors (TLRs) play an important role in sepsis, among which TLR4 has been widely studied and considered as a key molecule in the innate immune system, participating in the occurrence and development of sepsis." (PMID 36402943, 2022). "Another report suggested that cholesteryl ester transfer protein had the ability to disrupt the interplay of bacterial lipopolysaccharide and TLR4 (Toll-like receptor 4), thereby reducing the uncontrolled inflammatory response in sepsis." (PMID 36579569, 2022). "A recent study demonstrated that inhibition of TLR4 by resatrovid (TAK242) mitigated sepsis-induced kidney injury through inhibiting autophagy." (PMID 36188562, 2022). "We found that increased the expression levels of TLR4 in the ileal tissues of sepsis mice exacerbated intestinal damage, increased mortality rates, promoted the depletion of Paneth cell and reduced the expression of LYZ and DEF-5." (PMID 36088483, 2022). "During early sepsis, cell-wall components from bacteria activated TLR4 resulting in a “cytokine storm” of pro-inflammatory mediators generated, mainly via the mitogen-activated protein kinase and NF-κB pathways." (PMID 36088483, 2022). "In our work, we introduced a PLA assay to measure and quantify the activation of TLR4 by examining its phosphorylation in cell culture models and clinical samples of sepsis patients." (PMID 36230982, 2022). "The TLR4 expression by immunocompetent cells was significantly higher for patients developing sepsis during the period of treatment-induced neutropenia, and the levels were also higher in bacterial compared to fungal infections." (PMID 35163998, 2022). "LPS is a classic toll-like receptor 4 (TLR4) agonist which can induce an immediate and robust inflammatory response, thus stimulating activation of the innate immune system in human sepsis." (PMID 35038964, 2022). "LPS-induced (Lipopolysaccharide) TLR4-NFκB pathway activation plays an important role in sepsis-induced AKI." (PMID 35165294, 2022). "Since cardiac TLR4 activation is known to play a crucial role in the regulation of cardiac dysfunction during sepsis, we examined the effect of TLR4 inhibition on macrophage–cardiomyocyte crosstalk in terms of cardiac inflammation." (PMID 36555168, 2022). "The results revealed that SEP protected against E. coli-induced sepsis and augmented macrophages phagocytosis via TLR4 signaling." (PMID 35370674, 2022). "TLR4 is believed to be both a friend and foe since improperly regulated TLR4 signaling can result in the overactivation of immune responses leading to sepsis, acute lung injury, or pathologic chronic inflammation involved in cancer and autoimmune disease." (PMID 36678520, 2022). "We found that sepsis-induced FABP4 expression in RTECs was dependent on TLR4/c-Jun signaling activation, and FABP4 mediated tubular damage in septic AKI, by forming a positive feedback loop with c-Jun to amplify inflammation and apoptosis." (PMID 35410456, 2022).
Sepsis (continued). "Although the role of TLR4 in the development of sepsis remains debatable, investigations using TLR4 antagonists for the treatment of sepsis is still ongoing." (PMID 35986268, 2022). "Inhibition of Cav–1 Tyr14 phosphorylation and the resulting inactivation of TLR4 signaling in pulmonary vascular endothelial cells represented a strategy to prevent sepsis–induced lung inflammation and injury." (PMID 35911737, 2022). "In response to sepsis, Toll-like receptor 4 (TLR4) has been discovered to play a crucial role in activating an immune response." (PMID 35281916, 2022). "Accordingly, identifying new therapies to control the extreme inflammatory status in sepsis by focusing on TLR4 signaling and intestinal flora is an important research avenue." (PMID 35722155, 2022). "TLRs deficiency attenuated cardiac dysfunction in a mouse model through inhibition of sepsis-induced activation of TLR4 mediated NF-κB signaling pathways, and prevention of the macrophage and neutrophil infiltration." (PMID 36911241, 2022). "HMOX1, MAPK14, and TLR4 were significantly overexpressed in sepsis, compared with the control group (all P < 0.001)." (PMID 35844488, 2022). "LY96 has been identified as a target of eritoran tetrasodium, a TLR4 antagonist drug that has been indicated for the treatment of sepsis in several clinical studies." (PMID 36339397, 2022). "Endothelial inflammatory activation in sepsis can occur via recognition of bacterial products such as LPS by TLR4 and RIG-I, or through pro-inflammatory cytokines including TNFα produced by immune cells." (PMID 35634305, 2022). "TLRs (Toll-like receptors) family, especially TLR4, is a most important receptor in sepsis-induced AKI that exists extensively on the cell membrane of renal tubular epithelial cells." (PMID 35165294, 2022). "LPS specifically activates TLR4, which in turn induces systemic inflammation and even sepsis if the signal is excessive." (PMID 35731263, 2022). "TAK242 can selectively inhibit the TLR4 signaling pathway and reduce the release of various inflammatory factors in sepsis, thereby reducing the mortality of sepsis." (PMID 35891967, 2022). "Studies have demonstrated that leukocytes in women have lower expression of toll-like receptor 4 (TLR4) and lower cytokine production, clinically demonstrated by reduced sepsis rates among women." (PMID 35422759, 2022). "The active TLR4 on platelets reportedly induced platelet binding to adherent neutrophils, leading to the release of NETs in sepsis." (PMID 36438795, 2022). "Mechanistically, TLR4 blockage improved sepsis-induced kidney injury, as well as suppressed c-Jun phosphorylation and FABP4 expression, where c-Jun knockdown also inhibited LPS-stimulated FABP4 level." (PMID 35410456, 2022). "Myeloid differentiation factor-2 (MD2), a binding protein of lipopolysaccharide (LPS), has been found to be essential to LPS recognition and the subsequent mediation of toll-like receptor 4 (TLR4)-dependent sepsis and acute lung injury." (PMID 35279129, 2022). "CLP significantly increased 7-day mortality and was associated with a higher murine sepsis score (MSS), closely related with increased TLR4 expression." (PMID 36088483, 2022). "In cases of severe infection that leads to sepsis, TLR4 is upregulated, but another study reported a weak expression of TLR4 in low birth weight neonates." (PMID 36679931, 2022). "reduning injection protects against sepsis partly via inhibition of HMGB1/TLR4/NF-κB/MAPKs signaling pathways." (PMID 35720285, 2022). "TLR4 appears to be a promising therapeutic target in COVID-19, supported by the fact that TLR4 antagonists have been previously used in sepsis and in other antiviral contexts." (PMID 35682644, 2022). "During sepsis, miRNAs were observed to be mainly involved in the activation of TLR-4, leading to the production of pro-inflammatory cytokines (IL-6, IL-1, TNF) that cause endothelial dysfunction and organ damage." (PMID 36012630, 2022).